SOAT1 (sterol O-acyltransferase 1)
Diseases named in the same sentence as SOAT1 in open-access papers (continued):
Sharing a sentence is not in itself a finding about the gene and the disease.
glioblastoma (63 papers, 2012 to 2025). The most malignant astrocytic tumor (WHO grade IV). "LDs and SOAT-1 have also been proposed as potential biomarkers, given their overexpression in glioblastoma." (PMID 38539424, 2024). "It has been reported that SOAT1 is a potential drug target in adrenocortical carcinoma and glioblastoma." (PMID 34258555, 2021). "Inhibition of SOAT1 can suppresses glioblastoma growth via blocking SREBP‐1‐mediated lipogenesis." (PMID 40917390, 2025). "K604, another SOAT1 inhibitor, can also suppress the proliferation of U251-MG cells and downregulate the activation of Protein kinase B (Akt) and extracellular signal‐regulated kinase in proliferating glioblastoma cells." (PMID 35399707, 2022). "In this case, we selected SOAT1, an enzyme catalyzing the formation of fatty acid-cholesterol esters, which was indicated as a possible drug target in adrenocortical carcinoma and glioblastoma for our validation." (PMID 34258555, 2021). "In conclusion, inhibitors of SOAT1 and DGAT1 show promising efficacy in reducing LDs accumulation in glioblastoma cells." (PMID 40097417, 2025). "Inhibition of sterol O-acyltransferase 1 (SOAT1) blocks LDs formation and suppresses glioblastoma growth via blocking the sterol regulatory element-binding protein 1 (SREBP-1)-regulated FA synthesis pathway." (PMID 40097417, 2025). "The amplification of SOAT-1 has similar effects to DGAT-1/2, as they are both involved in lipid storage and propagate glioblastoma aggressiveness." (PMID 38539424, 2024). "Sterol O‐acyltransferase 1 (SOAT1) is a key enzyme which could convert endoplasmic reticulum (ER) cholesterol to cholesterol esters (CE) to store in lipid droplets (LDs), and inhibition of SOAT1 could effectively suppress SREBP‐1 and block glioblastoma growth." (PMID 34423480, 2021).
ovarian carcinoma (63 papers, 2011 to 2026). A malignant neoplasm originating from the surface ovarian epithelium. "Furthermore, knockdown of SOAT1 improved the cisplatin sensitivity of ovarian cancer cells." (PMID 34820325, 2021).
colon carcinoma (49 papers, 2002 to 2025). "In vitro and in vivo results further, demonstrate that nystatin synergizes with avasimibe-associated SOAT1 targeting in suppressing the viability of colon cancer cells." (PMID 33637695, 2021). "SOAT1 is also upregulated in colon cancer, enhancing the migration and invasion abilities of colon cancer cells to promote its progression (Wang XC." (PMID 40969353, 2025). "Nystatin, an inhibitor of cholesterol, synergizes with targeting SOAT1 in suppressing the viability of colon cancer cells." (PMID 35646697, 2022). "Through immunohistochemistry (IHC) analysis, SOAT1/2 levels were assessed in a colon cancer tissue microarray (TMA) comprising 66 matched pairs of carcinoma and normal tissue samples." (PMID 33637695, 2021). "Herein, we demonstrate that targeting SOAT1 promotes YAP expression by elevating cellular cholesterol content in colon cancer cells." (PMID 33637695, 2021). "Mechanistically, we found that nystatin had no obvious effect on YAP expression; however, it significantly lowered YAP expression under avasimibe or SOAT1 siRNA in colon cancer cells." (PMID 33637695, 2021). "Herein, we demonstrate how targeting SOAT1 promotes YAP expression by elevating cellular cholesterol content in colon cancer cells." (PMID 33637695, 2021). "Cholesterol-regulated signaling potentially mediates the resistance of colon cancer cells to SOAT1 inhibition." (PMID 33637695, 2021). "Moreover, nystatin synergized with the SOAT1 inhibitor avasimibe in suppressing the viability of colon cancer cells in vitro and in vivo." (PMID 33637695, 2021). "Thus, we deduced that targeting SOAT1 was dependent on cellular cholesterol to promote YAP expression in colon cancer cells." (PMID 33637695, 2021). "Compared to normal tissues, SOAT1 expression was significantly higher in colon tumor tissues." (PMID 33637695, 2021). "Furthermore, SOAT1 was inhibited by siRNA or avasimibe in SW1116 cells to elucidate whether it regulated LDs in colon cancer." (PMID 33637695, 2021). "Nystatin-mediated cholesterol sequestration could sensitize colon cancer cells to SOAT1 ablation." (PMID 33637695, 2021). "Notably, these findings could avail new mechanistic insights into the role of cholesterol in the Hippo/YAP pathway, uncover the basis of intrinsic resistance to SOAT1-targeted therapy, and suggest a novel approach for cholesterol metabolic-targeted treatment of colon cancers." (PMID 33637695, 2021). "Besides, in colon cancers, much lower SOAT2 was expressed than SOAT1." (PMID 33637695, 2021). "To validate whether targeting SOAT1 potentially elevates intracellular free cholesterol content as a mechanism for regulating YAP expression, we used β-cyclodextrin (β-CD) to extract cholesterol from colon cancer cells." (PMID 33637695, 2021). "Also, targeting SOAT1 promotes YAP expression by elevating cellular cholesterol content in colon cancer cells, whereas nystatin-mediated cholesterol sequestration inhibits YAP expression in the absence of SOAT1." (PMID 33637695, 2021).
Alzheimer disease (32 papers, 2010 to 2026). A progressive, neurodegenerative disease characterized by loss of function and death of nerve cells in several areas of the brain leading to loss of cognitive function such as memory and language. "Increased ACAT1/SOAT1 expression/activity in activated macrophages has been implicated in atherosclerosis, Alzheimer’s disease, and cancer." (PMID 40603564, 2025). "There have also been SOAT1 variants that are associated with Alzheimer’s disease." (PMID 34436484, 2021). "High levels of ACAT1/SOAT1 activity have been shown in a variety of disease conditions, including cancer, Alzheimer’s disease, and cardiovascular disease." (PMID 40603564, 2025). "Genetic knockout or pharmacological inhibition of SOAT1 have also been proved to provide several beneficial effects on Alzheimer’s disease." (PMID 37409263, 2023). "Knockout of mouse Soat1 or ACAT1 inhibitors has been found to decrease β-amyloid levels in mouse models of Alzheimer’s disease." (PMID 34436484, 2021). "Sterol O-Acyltransferase 1 (Soat1) plays an important role in cholesterol homeostasis regulation and metabolism, and it has been extensively studied as a target for hypercholesterolemia and Alzheimer's disease." (PMID 30705647, 2018). "For example, it has been previously observed that MAMs are altered in Alzheimer’s disease, and this correlates with higher ACAT1/SOAT1 activity and cholesterol accumulation within the MAM, similar to what is observed here." (PMID 36982602, 2023). "The finding of no SOAT1 GWAS SNPs associated with lipoprotein levels, atherosclerotic disease, or Alzheimer’s disease, which have been the objectives of large, well-powered GWAS studies, indicates that the SOAT1 expression levels do not play a significant role in these phenotypes." (PMID 34436484, 2021).
liver cancer (31 papers, 2017 to 2025). An epithelial or non-epithelial malignant neoplasm that arises from the liver. "In particular, nilotinib displayed a high affinity for SOAT1 protein and significantly inhibited tumor activity both in vitro and in vivo, highlighting their clinical potential in the treatment of liver cancer." (PMID 35941608, 2022). "The primary aim of this research was to continue the preliminary work of the laboratory and develop a high-throughput, ligand screening technology for the identification of potential therapeutic targets of SOAT1 protein for S-III liver cancer patients." (PMID 35941608, 2022). "Taken together, we reported several high-affinity SOAT1 ligands and demonstrated their clinical potential in the precision therapy of liver cancer, and also reveal the potential antitumor mechanism of SOAT1-targeting compounds." (PMID 35941608, 2022). "Here, we performed proteomic analysis on the liver cancer cell line HepG2 treated with SOAT1-targeting compounds and tried to clarify the connection between cholesterol homeostasis regulation and tumors and the role of cholesterol homeostasis regulatory proteins in tumorigenesis and development." (PMID 35941608, 2022). "The two cancer types bearing the highest SOAT1 alteration frequency in TCGA pan-cancers were cholangiocarcinoma (CHOL) and LIHC, both of which belong to liver cancer." (PMID 34052835, 2021).
Parkinson disease (27 papers, 2015 to 2026). A progressive degenerative disorder of the central nervous system characterized by loss of dopamine producing neurons in the substantia nigra and the presence of Lewy bodies in the substantia nigra and locus coeruleus. "Given the pivotal role of the SOAT1/ACAT1 gene in cholesterol esterification as well as its important role in the progression of neurodegenerative diseases, such as AD and Parkinson’s disease, RNA and protein measurement validation experiments were focused on SOAT1/ACAT1." (PMID 30390000, 2018).
measles (25 papers, 2016 to 2025). A highly contagious viral infection caused by the measles virus. "In measles, including six in whole blood (SOAT1, COLGALT2, AC021860.1, HCG11, METTL21B, and MRPL10), six in the lung tissue (GSTM4, PAQR6, RP11-617D20.1, SNX8, METTL21B, and ANKRD27), and two in the transformed fibroblast cells (CBWD2, and TSFM)." (PMID 37020999, 2023).
ZIKV infection (22 papers, 2017 to 2025). "Concurrent with reduced virus production, knockdown of DGAT1 or SOAT1 in Huh7 cells diminished viral RNA and protein level, indicating that loss of either enzyme reduced ZIKV infection rates." (PMID 39237833, 2024). "In contrast to DGAT, inhibition of SOAT1, especially with the more potent ATR-101 inhibitor, reduced ZIKV infection in all our cell culture models, indicating that SOAT1 activity is critical to ZIKV." (PMID 39237833, 2024). "In follow-up experiments we specifically identified SOAT1 as a druggable target to limit ZIKV infection in diverse cell lines as well as human cerebral organoids." (PMID 39237833, 2024). "Further, our findings highlight SOAT1 as druggable host factor for ZIKV infection in various cell types and point towards a potential pan-orthoflavivirus target." (PMID 39237833, 2024). "In SH-SY5Y cells, SOAT1 inhibition with high dose ATR-101 slightly reduced ZIKV infection, but to a lesser extent compared to the other cell lines we used." (PMID 39237833, 2024). "ZIKV infection induces SOAT1 and SOAT2, increasing the amount of cholesteryl esters." (PMID 41306517, 2025). "Importantly, inhibition of SOAT1 severely impairs ZIKV infection in neural cell culture models and cerebral organoids." (PMID 39237833, 2024). "ZIKV infection significantly upregulated SOAT2 mRNA levels, while SOAT1 mRNA levels showed less pronounced increase that occurred only at 24 hours post infection." (PMID 41306517, 2025). "Supplementation with cholesteryl oleate did not affect ZIKV CPE in SOAT1i-treated cells, indicating that the observed reduction in ZIKV infection after SOAT1 inhibition was not due to reduced cellular levels of cholesterol ester." (PMID 39237833, 2024). "Taken together, whereas DGAT inhibition is not antiviral in our cell culture models, SOAT1 activity is critical for ZIKV replication in primary target cells of ZIKV infection." (PMID 39237833, 2024). "However, the respective study generated only one monoclonal SOAT1/2 knockout cell line using CRISPR/Cas and it is even stated that the increase in ZIKV infection is likely not due to free cholesterol levels." (PMID 39237833, 2024).
osteosarcoma (20 papers, 2016 to 2026). A usually aggressive malignant bone-forming mesenchymal neoplasm, predominantly affecting adolescents and young adults. "Prior studies show efficacy of statins, BET/CDK7 inhibitors, and SOAT1 blockade (e.g., avasimibe) in osteosarcoma or related cancer models, with SREBP-axis inhibitors (e.g., fatostatin) providing complementary upstream control." (PMID 41358198, 2025).
renal fibrosis (18 papers, 2018 to 2025). A final common manifestation of a wide variety of chronic kidney diseases characterized by glomerulosclerosis and tubulointerstitial fibrosis. "As the TGFβ/SMAD pathway is a major pathway in renal fibrosis in aging, diabetic, and ischemic kidneys, this pathway might also be involved in the upregulation of SOAT1 expression in our model." (PMID 36555105, 2022). "Third, SOAT1 blockade may improve renal fibrosis and inflammation via the protection of renal resident cells, such as podocytes." (PMID 36555105, 2022). "Treatment with avasimibe, a SOAT inhibitor, ameliorated TLT maturation and renal fibrosis in mice, suggesting that targeting SOAT1 may represent a novel therapeutic strategy for TLT-related kidney disease." (PMID 36555105, 2022).
cytomegalovirus infection (16 papers, 2019 to 2026). A herpesvirus infection caused by Cytomegalovirus. "Accordingly, SOAT1, responsible for intracellular CE biosynthesis from cholesterol and fatty acyl-CoA, was shown to be upregulated early upon HCMV infection, and its inhibition restrained viral replication." (PMID 35420480, 2022). "SOAT1 gene expression increased upon HCMV infection, confirming previous studies." (PMID 35420480, 2022). "To determine whether SOAT1 gene expression was affected by HCMV replication and/or IFI16 sensor activity, we examined its mRNA expression pattern during a time course of HCMV infection of WT and IFI16 KO HFFs." (PMID 35420480, 2022).
neuroblastoma (15 papers, 2017 to 2025). Neuroblastoma (NB) is the most common solid, extracranial childhood tumor. "SOAT1-mediated LDs formation plays a role in 24S-OHC-induced cell death, and knocking down SOAT1 can reduce 24S-OHC-induced cell death in human neuroblastoma SH-SY5Y cells." (PMID 40097417, 2025). "To investigate the SOAT1-dependency of ZIKV in other neural cell types, we next infected astrocytoma (1321N1) and neuroblastoma cells (SH-SY5Y) and treated them with DGAT and SOAT1 inhibitors." (PMID 39237833, 2024).
heart failure (14 papers, 2017 to 2025). Inability of the heart to pump blood at an adequate rate to meet tissue metabolic requirements. "And piRNA-6426 alleviates hypoxia-induced cardiomyocyte dysfunction and heart failure in rats by regulating DNMT3B-mediated methylation of SOAT1 promoter, it provides a new direction for the treatment of HF." (PMID 35354120, 2022).
pancreatic ductal adenocarcinoma (12 papers, 2017 to 2025). An infiltrating adenocarcinoma that arises from the epithelial cells of the pancreas. "SOAT1 inhibition can inhibit pancreatic ductal adenocarcinoma (PDAC) progression by activating cholesterol-mediated negative feedback of the mevalonate pathway." (PMID 35646697, 2022).
Stroke (11 papers, 2011 to 2026). Sudden impairment of blood flow to a part of the brain due to occlusion or rupture of an artery to the brain. "SOAT1 was up-regulated among tibolone users, in accord with the known increased risk of stroke associated with tibolone use." (PMID 21453500, 2011).
adrenocortical carcinoma (10 papers, 2018 to 2025). "On the contrary, SOAT1 expression was low in adrenocortical carcinoma (ACC), lung squamous cell carcinoma (LUSC), and pheochromocytoma and paraganglioma (PCPG)." (PMID 37304239, 2023). "More importantly, nevanimibe HCl, a novel SOAT1 inhibitor, was used in a phase 1 study of adrenocortical carcinoma." (PMID 35821230, 2022). "In this study, we analyzed the expression of SOAT1, recently identified as the target molecule of mitotane, which is approved as an orphan drug for the treatment of adrenocortical carcinoma." (PMID 35409086, 2022). "We have previously shown that SOAT1 inhibition is the main molecular mechanism of mitotane, the only drug approved for treatment of adrenocortical carcinoma." (PMID 34326474, 2022). "Mitotane is the only FDA-approved SOAT1 inhibitor and is in clinical use for the treatment of the orphan disease adrenocortical carcinoma." (PMID 35409086, 2022). "We have used mitotane to inhibit SOAT1, which is already known for the treatment of adrenocortical carcinoma and Cushing’s syndrome." (PMID 33420254, 2021). "Sterol-O-Acyl Transferase 1 (SOAT1), a key enzyme in the conversion of endoplasmic reticulum cholesterol to esters for storage in lipid droplets (LD), serves as a target for the orphan drug mitotane to treat adrenocortical carcinoma." (PMID 35409086, 2022). "As SOAT1 is the target of mitotane, a drug used for the treatment of adrenocortical carcinoma, it would be interesting to investigate whether SOAT1 inhibition could also interfere with cholesterol metabolism in PCa cells." (PMID 34417456, 2021). "The highest level of SOAT1 expression was observed in adrenocortical carcinoma (ACC), and the lowest in thymoma (THYM)." (PMID 37304239, 2023). "Mitotane, an inhibitor of SOAT1, is an FDA-approved small molecule drug commonly used to treat adrenocortical carcinoma." (PMID 34258555, 2021). "The selective SOAT1 inhibitor nevanimibe (ATR-101, PD132301-2) has been investigated for the treatment of adrenal disorders and was recently tested in a phase I clinical trial against adrenocortical carcinoma." (PMID 34326474, 2022). "Of note, SOAT1 expression was not reported in the study cohort although SOAT1 expression was shown to be very heterogenous in adrenocortical carcinoma." (PMID 34326474, 2022).
Hepatic steatosis (9 papers, 2018 to 2025). Steatosis is a term used to denote lipid accumulation within hepatocytes. "Moreover, nootkatone supplementation reduced the expression of SOAT1, alleviated hepatic steatosis and pathological injuries damage, which suppressed tumorigenesis and development of NAFLD-HCC." (PMID 38724499, 2024). "We further revealed HFD-promoted hepatic steatosis and HCC progression through SOAT1." (PMID 34052835, 2021).
Hypercholesterolemia (8 papers, 2014 to 2022). An increased concentration of cholesterol in the blood. "Recent studies have shown that the deletion of the SOAT1 gene in macrophages results in an increase in atherosclerotic lesion area in the aortas of hypercholesterolemia mice." (PMID 31684966, 2019). "Previous studies have demonstrated that SOAT1 was involved in the formation of atherosclerotic plaques, and thus might be a promising target for atherosclerosis and hypercholesterolemia treatment." (PMID 24906453, 2014).
metastatic tumors (8 papers, 2011 to 2025). "Our statistical analysis revealed that the expression level of SOAT1 was higher in LN-metastatic tumors and was positively correlated with the expression level of VEGFC, VEGFR3 and LYVE-1, which are lymphangiogenic growth factors." (PMID 34790132, 2021).
dyslipidemia (7 papers, 2017 to 2025). "While dyslipidemia and cholesterol accumulation have been strongly implicated in promoting pathological NV in models of subretinal NV15, not much is known about role of cholesterol metabolism, activation of ACAT1/SOAT1, and CE formation in pathological RNV during ischemic retinopathy." (PMID 40603564, 2025).
non-alcoholic fatty liver disease (7 papers, 2022 to 2025). "Decreased expression of Lxra in the liver has been documented in non-alcoholic fatty liver disease, often seen in the aged population, and a decreased pattern of Soat1 might be related to dysregulation of cholesterol esters synthesis." (PMID 41049368, 2025).